GSDMD (gasdermin D)
Diseases named in the same sentence as GSDMD in open-access papers (continued):
Sharing a sentence is not in itself a finding about the gene and the disease.
psoriasis (continued). "Given the particular elevation of GSDMD levels in psoriasis, we questioned whether GSDMD contributed to psoriasis pathogenesis." (PMID 39717896, 2024). "Yet, whether other gasdermin proteins except GSDMD involve in the pathogenesis and progression of psoriasis remains unknown." (PMID 38429278, 2024). "(a) Expression of GSDMD in neutrophils in psoriasis patients and healthy people from GSE123785." (PMID 39717896, 2024). "Consistent with earlier research, our study found that the expression of GSDMD and its upstream molecule caspase 1 was upregulated in the skin of psoriasis patients and psoriasis-like mice, indicating that the pyroptosis pathway is activated in psoriasis skin lesions." (PMID 39717896, 2024). "However, considering our results, serum or urinary GSDMD cannot become a psoriasis biomarker at this time because both were insignificantly elevated in patients." (PMID 37685853, 2023). "Taking into consideration the documented role of gasdermins in cell proliferation and death, the increased expression of GSDMD in psoriatic skin may demonstrate the potential involvement of this protein in psoriasis pathogenesis." (PMID 37685853, 2023). "GSDMD-mediated pyroptosis is activated in keratinocytes of psoriatic lesion; both GSDMD knockout and pyroptosis inhibitor disulfiram alleviate imiquimod-induced psoriasis-like lesions in mice." (PMID 37762693, 2023). "Understanding the role of gasdermins in the death and proliferation of cells, we propose their engagement in psoriasis pathogenesis based on the activation of caspases, which results in the cleavage of GSDMD, leading to the release of pro-inflammatory cytokines and epidermal hyperproliferation." (PMID 37685853, 2023). "Besides, caspase-11 contributed to the pathogenesis of imiquimod-induced psoriasis in mice through the mediation of GSDMD activation and cell death." (PMID 35720396, 2022). "Furthermore, we found that inhibiting GSDMD-mediated keratinocyte pyroptosis by topical application of disulfiram can effectively retrieve development of psoriasis-like dermatitis in mice model, suggesting that targeting pyroptosis can be considered as a therapeutic strategy." (PMID 37673869, 2023). "Besides promoting keratinocyte proliferation, mediating secretion of DAMPs and cytokines might be another key mechanism by which GSDMD-mediated pyroptosis participates pathogenesis and development of psoriasis." (PMID 37673869, 2023). "In contrast, psoriasis skin-derived S.B cells expressed high levels of pyroptosis-related genes, such as CASP1, CAPS8, GSDMA, GSDMB, and GSDMD." (PMID 35962439, 2022). "The absence of a strong correlation between GSDMD levels and clinical severity in HS contrasts with findings in psoriasis, where pyroptosis directly contributes to disease progression." (PMID 41007405, 2025). "In this study, we found that gasdermin D (GSDMD) is higher in human psoriatic skin than that in normal skin, and in imiquimod-induced psoriasis-like mouse skin, the expression of Gsdmd was most significantly altered in neutrophils and Il1b was also mainly expressed in neutrophils." (PMID 39717896, 2024). "In addition, there are some studies on pyroptosis-related proteins upstream of GSDMD, such as NLPR3 inflammasome and AIM2 inflammasome, which are involved in and promote psoriasis through downstream inflammatory cytokines." (PMID 39717896, 2024). "We proved that GSDMD is significantly most-expressed in psoriatic plaques and insignificantly elevated in the serum of patients with psoriasis compared to controls without psoriasis." (PMID 37685853, 2023). "Gasdermins have been poorly investigated in psoriasis so far and both the serum and urinary concentrations and tissue expression of GSDMD in immunohistochemistry have never been studied in this disease." (PMID 37685853, 2023).
psoriasis (continued). "More importantly, protein levels of N-GSDMD and IL-1β (a key secretory cytokine through GSDMD-mediated pyroptosis) were significantly increased in epidermal lysates of skin lesion tissue samples from patients with psoriasis but not in epidermal lysates from normal skin tissue samples." (PMID 37673869, 2023). "Neither serum, nor urinary GSDMD can be currently considered a psoriasis biomarker; however, future studies may change this perspective." (PMID 37685853, 2023). "Notably, although neutrophil-specific deletion of GSDMD mice showed a reduction in psoriasis-like symptoms after induction, the reduction was not as pronounced as in GSDMD full knockout mice, suggesting that additional cellular pyroptosis may also be involved in psoriasis pathogenesis." (PMID 39717896, 2024). "In our recent papers, we have proved that GSDMD and GSDME could be involved in the pathogenesis of psoriasis and also potentially become a novel marker of psoriasis." (PMID 38693919, 2024).
Yersinia infection (20 papers, 2019 to 2026). "Recent studies revealed an alternative pyroptosis pathway executed by GSDMD during pathogenic Yersinia infection driven by a receptor-interacting protein 1 (RIP1)-caspase 8 signaling cascade, which is independent of inflammasomes." (PMID 36248872, 2022). "Inflammatory caspase-1 initiates apoptosis in GSDMD deficient cells via the Bid-caspase-9-caspase-3 axis, and caspase-8 cleaves GSDMD during Yersinia infection to induce pyroptosis." (PMID 36159393, 2022). "Yersinia infections in macrophages trigger caspase-8 cleavage of GSDMD, which in turn initiates pyroptosis, and granzyme A, a lymphocyte-derived enzyme, cleaves GSDMB, which in turn triggers pyroptosis in a number of cancer cell types." (PMID 39655049, 2024). "Caspase‐8, an initiator of the extrinsic apoptosis pathway, has recently been reported by two independent groups to cleave GSDMD to induce pyroptosis during Yersinia infection." (PMID 37125240, 2023). "Caspase-8 can also cleave GSDMD to activate pore formation and cell death during Yersinia infection." (PMID 35563804, 2022). "In contrast, in Yersinia infection model, like we observed in this study, caspase-8 activates GSDMD to induce cell death." (PMID 36532444, 2022). "Caspase‐8 was indicated to induce cleavage of GSDMD to activate pyroptosis during Yersinia infection." (PMID 34459122, 2021). "Yersinia infection triggered caspase-8-mediated GSDMD cleavage and subsequent pyroptotic cell death, whereas the apoptotic pathway was restrained." (PMID 31492049, 2019). "Consistent with this, a recent report highlighted that RIPK1-dependent caspase-8 activation leads to GSDMD cleavage and pyroptosis in response to Yersinia infection and that alternative pathways including caspase-11 are recruited when RIPK1 or caspase-8 is impaired." (PMID 41596270, 2026). "Additionally, caspase-3 and caspase-8-dependent pathways can induce pyroptosis: chemotherapeutic agents trigger pyroptosis via caspase-3-mediated cleavage of GSDME, while Yersinia infection induces pyroptosis through caspase-8-mediated cleavage of GSDMD." (PMID 40832104, 2025). "Interestingly, in addition to the active p30 fragment, it is also observed that GSDMD was cleaved into a p43 and p20 fragment upon Yersinia infection or LPS/TNF‐α/TAK1 inhibitor co‐stimulation." (PMID 33033617, 2020). "Besides caspase-3–dependent pyroptosis, recent study indicated the apoptotic caspase-8 induces cleavage of GSDME and GSDMD to elicit pyroptosis during Yersinia infection, which implied that pyroptosis and apoptosis share many signal transduction pathways." (PMID 30804337, 2019). "This may contribute to the restriction of caspase-1-dependent GSDMD cleavage during Yersinia infection." (PMID 31492049, 2019). "Interestingly, upon TLR or death receptor activation, active caspase-8 can cleave the IL-1β precursor into its bioactive fragment at the same site as caspase-1, and can directly cleave GSDMD into its N-terminal fragment, triggering pyroptosis during Yersinia infection." (PMID 36532444, 2022). "In certain settings such as during Yersinia infection of macrophages, CASP8 is able to substitute for pro-pyroptotic CASP1 and CASP11 to cleave GSDMD and execute death." (PMID 33126536, 2020). "In contrast to GSDMD, GSDME can be cleaved via caspase‐3 in macrophages during Yersinia infection or LPS/TNF‐α/TAK1 inhibitor co‐stimulation." (PMID 33033617, 2020). "In the context of Yersinia infection, RIPK1 is necessary for activation of caspase-1, GSDMD, caspase-8, caspase-3, and caspase-7, but it negatively regulates the activation of MLKL, highlighting the multifaceted modulation of cell death effectors that can occur within PANoptosis." (PMID 35563804, 2022). "Although CASP8 has traditionally been considered as a pivotal apoptotic initiator, accumulating studies have revealed the nonapoptotic roles of CASP8 as initiating cleavage of GSDMD during Yersinia infection." (PMID 32295623, 2020).
Yersinia infection (continued). "Interestingly, although some researchers had already identified GSDMD and GSDME activation downstream of caspase-8 after Yersinia infection, in the context of mitochondrial apoptosis, NLRP3 activation induced by K+ efflux seemed to be independent of GSDMD." (PMID 33785842, 2021).
acute kidney injury (19 papers, 2021 to 2025). Sudden and sustained deterioration of the kidney function characterized by decreased glomerular filtration rate, increased serum creatinine or oliguria. "Collectively, these data indicate that genetic deficiency of the pyroptosis executor protein GSDMD sensitizes to acute kidney injury in three independent rodent models." (PMID 36109515, 2022). "Recent studies indicate a significant upregulation of gasdermin D (GSDMD) in acute kidney injury (AKI), a severe medical condition characterized by high morbidity and mortality globally." (PMID 39188700, 2024). "Studies have further shown the effect of GSDMD-mediated pyroptosis in different acute kidney injuries." (PMID 36967609, 2023). "GSDMD has been recently identified as a pyroptotic executioner, which can participate in the numerous diseases, such as acute kidney injury, alcoholic hepatitis, or neuroinflammation." (PMID 35350176, 2022). "Deletion of GSDMD significantly ameliorate cisplatin-induced acute kidney injury in mice, whereas mice with GSDMD-N fragment overexpression in the kidney are more vulnerable to acute kidney injury caused by cisplatin." (PMID 33941231, 2021). "A latest study revealed that GSDMD-mediated pyroptosis in mouse kidney tissues and renal tubular epithelial cells may contribute to cisplatin-induced acute kidney injury." (PMID 33941231, 2021). "Studies on GSDMD-deficient mice indicate heightened vulnerability to injury in both IRI and cisplatin-induced acute kidney injury (AKI) models." (PMID 38740765, 2024). "GSDMD-NT was activated in acute kidney injury (AKI) and renal tubular cell injury induced by the chemotherapeutic agent cisplatin, leading to pyroptosis and renal inflammatory response." (PMID 36967609, 2023). "Pyroptosis emerged via NLRP3 inflammasome activation and GSDMD/GSDME cleavage, exacerbating inflammation and overt renal failure." (PMID 41301789, 2025). "However, emerging literature has proven that caspase-11/GSDMD-mediated noncanonical pyroptosis is involved in acute kidney injury and hepatic injury induced by some endogenous pathophysiological factors including I/R injury." (PMID 34975487, 2021). "During acute kidney injury (AKI) and renal fibrosis induced by nondiabetic renal disease, the mechanism of pyroptosis involves classical pyroptosis in the caspase-1/GSDMD pathway as well as nonclassical pyroptosis in the caspase-4/5/11 pathway." (PMID 39000237, 2024).
Obesity (19 papers, 2021 to 2026). Accumulation of substantial excess body fat. "A recent study demonstrated that Gasdermin D-mediated release of IL-33 from senescent hepatic stellate cells facilitates obesity-associated HCC." (PMID 37481543, 2023). "In the present study, we investigated whether GSDMD is involved in the regulation of adipose tissue function and the development of obesity-induced metabolic disease using GSDMD-deficient mice." (PMID 36065376, 2022). "We first examined whether a deficiency in GSDMD could influence the development of obesity in mice fed NCD or HFD for 30 weeks." (PMID 36065376, 2022). "However, the potential role of GSDMD in adipose tissue and the underlying mechanism in obesity remain unknown." (PMID 36065376, 2022). "In mouse models of obesity-induced liver cancer, senescent hepatic stellate cells generate pores through caspase-11-mediated cleavage of GSDMD, allowing extracellular secretion of IL-1β and its family member IL-33." (PMID 39994107, 2025). "Obesity, a significant risk factor for pancreatic cancer, induces macrophage pyroptosis through saturated fatty acids mediated by FABP4 in a caspase-1/ GSDMD-dependent manner." (PMID 39994107, 2025). "Inflammasomes are also involved in the cleavage of gasdermin-D (GSDM-D), the induction of pyroptosis, and obesity-induced inflammation." (PMID 36674982, 2023). "Studies have found that when obesity occurs, GSDMD interacts with interferon regulatory factor 7 and forms a complex to promote adipocyte pyroptosis." (PMID 37125240, 2023). "Since obesity is associated with the development of insulin resistance, we next determined the effect of HFD on glucose and insulin tolerance in WT and GSDMD KO mice." (PMID 36065376, 2022). "The knockdown of integrin α5β1 attenuated FFA-induced caspase-1 cleavage and excessive lipid accumulation, reducing HMGB1 and GSDMD-NT protein levels, indicating its participation in pro-inflammatory pyroptosis during obesity." (PMID 36145246, 2022). "In contrast, DSF robustly protects against obesity and IR through a GSDMD-independent mechanism." (PMID 41726890, 2026). "On the contrary, the relative abundance of PCSK9 and NLRP3 positively correlated with obesity diagnosis indices (body weight, fat mass and Lee’s index), abnormal sperm rate, pyroptosis markers including Caspase-1, GSDMD, IL-1, IL-18 and the level of lipid metabolizing hormone (TG, TC and LDL)." (PMID 37935689, 2023). "Therefore, understanding the mechanism governing the role of GSDMD in obesity will assist in understanding low-level adipose tissue inflammation and provide new ideas for developing therapeutics against obesity and related metabolic diseases." (PMID 36065376, 2022). "However, the role of the NLRP3 inflammasome in IL-1β release through GSDMD pores during obesity-induced IR in skeletal muscle tissue remains unexplored." (PMID 34638553, 2021). "Although this study did not deepen our understanding of the molecular mechanisms behind these positive effects, the anti-obesity properties of this drug offer interesting ways to study GSDMD function in highly metabolic tissues affected by obesity, as in the case of skeletal muscle." (PMID 33806797, 2021). "Another study displays that it can inhibit obesity-induced excessive activation of Caspase-1 in stellate sympathetic ganglion, whereas activated Caspase-1 can cleave GSDMD into C- and N-terminal, in which GSDMD-NT, as the pyroptotic executioner, induces proinflammatory cell death." (PMID 40915382, 2025). "However, whether GSDMD is involved in the regulation of adipose tissue function and the development of obesity-induced metabolic disease remains unknown." (PMID 36065376, 2022). "By targeting GSDMD, MT inhibits the activation of NLRP3 inflammasome in adipose tissue of mice and inhibits pyroptosis to alleviate obesity." (PMID 37125240, 2023).
Obesity (continued). "Here, we demonstrate that GSDMD is dispensable for high-fat diet-induced obesity and insulin resistance, as neither genetic deletion nor antisense-mediated inhibition of GSDMD confers metabolic protection." (PMID 41726890, 2026). "In this work, we address the hypothesis that during obesity-induced IR, there is an increase in the NLRP3 inflammasome complex, IL-1β, and GSDMD protein content in the skeletal muscle." (PMID 34638553, 2021). "Altogether, these findings indicate that GSDMD is not required for HFD-induced adipose tissue inflammation, suggesting that other GSDMD-independent mechanisms play a dominant role in mediating adipose tissue inflammation associated with obesity." (PMID 36065376, 2022).